IL6 (interleukin 6)
Diseases named in the same sentence as IL6 in open-access papers (continued):
Sharing a sentence is not in itself a finding about the gene and the disease.
Obesity (continued). "In particular, three studies found an association between vegetable and fruit intake and lower levels of CRP, and IL-6 and TNF-α, both in healthy males and females, as well as in males and females with obesity." (PMID 33503979, 2021). "Acute-phase protein CRP is synthesized by hepatocytes and released into the circulation in response to inflammatory stimuli, including TNF and IL-6, synthesized by WAT macrophages and adipocytes in obesity." (PMID 34834553, 2021). "In mice, HFD-induced obesity increased macrophage infiltration and expression of pro-inflammatory cytokines such as tumor necrosis factor α (TNF-α) and interleukin 6 (IL-6) in mesenteric WAT, and increased TNF-α expression in the gut." (PMID 34938153, 2021). "For example, in 97 patients with obesity underwent either RYGB or biliopancreatic diversion with duodenal switch, decreased levels of IFN-γ, hs-CRP, TNF-α, IL-13, IL-6, IL-1ra, C3, and leptin were described compared with baseline levels at 1-year follow-up55." (PMID 34108550, 2021). "MMe macrophages secreted IL-6 in a NOX2-dependent manner through combining with GP130 on TNBC cells to promote stem-like properties and tumorigenesis during obesity." (PMID 34350120, 2021). "In obesity-related kidney disease, several adipokines have been implied such as leptin, adiponectin, tumor necrosis factor α (TNF-α) or interleukin 6 (IL-6)." (PMID 33928108, 2021). "Additionally, results from animal models reveal that interleukin 6 (IL-6) overexpression may not only be a consequence but also a central causal factor of NAFLD regardless of the presence of overweight/obesity." (PMID 34680463, 2021). "Obesity is a chronic low-grade inflammatory condition that stimulates inflammatory cytokine release, such as tumor necrosis factor (TNF-α), interleukin-6 (IL-6), and C-reactive protein (CRP)." (PMID 34258058, 2021). "In line with our results, the expression of the IL-6 protein in epicardial AT (EAT) was recently reported as unchanged in T2DM and obesity." (PMID 34203452, 2021). "The levels of serum fibrinogen and other acute phase reactants, such as TNF-α, IL-6, and CRP were demonstrated to be increased in obesity." (PMID 34176464, 2021). "In our study, the ELISA data illustrated the effects of MLB supplementation on IL-6 and TNF-α levels in the serum of mice with HFD-induced obesity." (PMID 35010979, 2021). "Obesity-induced chronic inflammation has been detected in obesity-induced IR, and some inflammatory cytokines such as CRP, IL-6, TNF-α, and MCP1 are found in obesity-induced IR." (PMID 33781239, 2021). "RASE1 suppressed the NF-κB pathway and proinflammatory cytokines IL-10, IL-6, and TNF-α levels in mice which involve inflammation and progression of obesity." (PMID 34812408, 2021). "Consistent with our study, type 2 diabetes mellitus, obesity, and insulin resistance result in persistent production of proinflammatory cytokines such as TNF-α, IL-1β, and IL-6, which typically inhibit adipogenesis." (PMID 34051860, 2021). "CDCP1, FGF23, HGF and IL-6 still had more prominent positive associations with %BF in overweight compared to normal weight subjects and the coefficients did not indicate that the associations were driven by obesity, whereas MCP-1 had a clear positive association with %BF only in the obese group." (PMID 34059769, 2021). "Furthermore, the analysis of inflammatory markers associated with male sexual function (i.e. as occurs in asymptomatic MAGIs) and oxidative stress (as i.e. interleukin (IL)-6 and IL-8) could be useful to better clarify if in the male obesity, accessory glands secretory function may be also altered." (PMID 34393997, 2021). "RASE1 suppressed NF-κB, pathway and proinflammatory cytokines IL-10, IL-6, and TNF-α level, which are involved in inflammation and progression of obesity." (PMID 34812408, 2021).
Obesity (continued). "The development of chronic, low-grade systemic inflammation is present early in both T2D and obesity, where pro-inflammatory cytokines are released from M1-type macrophages (TNF-α, IL-6, IL-12, IL-18)." (PMID 33924876, 2021). "Obesity correlates with elevated insulin levels, free IGFs, and adipocyte-derived factors, including leptin, the tumor necrosis factor-alpha (TNF-α), and interleukin-6 (IL-6)." (PMID 34298805, 2021). "Because remarkable similarities between adipose expansion and growth of solid tumors have been observed, we evaluated the in vivo IL-6 dependency of IDO1 expression and activity in obesity." (PMID 34394118, 2021). "Increased levels of both factors, IL-6 and TNF-α, have been diagnosed in people with obesity and osteopenia." (PMID 34279426, 2021). "In this context, obesity and CC also increased the levels of relevant inflammation and ECM remodelling factors including IL-6, OPN, YKL-40 and VEGFA." (PMID 34445187, 2021). "At baseline, men with vitamin D deficiency had a more adverse health profile including the highest prevalence of smoking, heavy drinking, physical inactivity, obesity, hypertension and the highest mean CRP and IL-6 (markers of inflammation)." (PMID 34933860, 2021). "Our results showed higher plasma levels of IL-6, IL-1β, TNF-α, IL-8, IL-12, and IL-18 in subjects with obesity before bariatric surgery when compared with the postoperative state." (PMID 34108550, 2021). "Macrophages in CLS produce inflammatory mediators, including TNF, IL-1β, IL-6, and PGE2, which contributes to the characterization of obesity as a state of chronic low-grade inflammation." (PMID 33859943, 2021). "Taking into account that IL6 was found to be elevated in obese individuals, but also in the setting of type 2 diabetes mellitus and insulin resistance, we might emphasize that this interleukin could represent a ‘bridge’ between obesity and obesity-related systemic complications." (PMID 34207683, 2021). "Significant alterations in chronic inflammation, particularly driven by persistent innate cytokine responses from adipocytes including IL-6, TNF-α, Type 1 IFN, and Leptin (modified from Alarcon, 2021), have been noted in the setting of obesity." (PMID 34835041, 2021). "IL-6 and TNF-α are cytokines that links the obesity and liver cancer through chronic inflammation and contribute for development of chronic low-grade systemic inflammation." (PMID 34535145, 2021). "As results, molecular docking findings indicated the binding capability of metformin with key proteins, including interleukin 6 (IL-6) and chemokine (C-C motif) Ligand 2 (CCL2) expressed in obesity- and hypertension-dependent tissues." (PMID 34334083, 2021). "Although it is known that hepcidin increases when interleukin 6 (IL-6) increases, the relationship between hepcidin, dyslipidemia, insulin resistance (IR) and visceral adiposity index (VAI) in adolescents with obesity is unclear." (PMID 34065056, 2021). "Obesity is regarded as a state of low-grade systemic inflammation, where high levels of tumour necrosis factor-α (TNF-α), interlukin-6 (IL-6) and leptin have been observed in obese compared to normal adipocytes." (PMID 34616553, 2021). "Notably, the mechanism(s) triggering abnormally high IL-6 levels in obesity remain unclear." (PMID 34831450, 2021). "Pregravid obesity is marked by elevated circulating levels of inflammatory mediators C-reactive protein (CRP) and IL-6, subclinical endotoxemia, and signs of heightened inflammation in the adipose tissue compartment." (PMID 34195568, 2021). "NF-κB pathway and proinflamatory cytokines such as IL-10, IL-6, and TNF-α promote inflammation and exacerbate obesity." (PMID 34812408, 2021). "Thus, it can be postulated that IL-6 polymorphisms may be significant in severely affected patients, but not in low-grade obesity." (PMID 34680892, 2021).
Obesity (continued). "In an animal model, obesity was shown to be related to an inflammatory status by secreting proinflammatory cytokines such as TNF-α and interleukin-6." (PMID 33407178, 2021). "The levels of interleukin‐6 (IL‐6) in AT is about 100 times higher than that in plasma, and high mobility group box 1 (HMGB1) secretion in AT of patients with obesity is twice as higher than in normal‐weight individuals." (PMID 33332766, 2021). "In obesity and type 2 diabetes mice, the interactions between TNF-a and IL-6 aggravate oxidative stress and contribute to coronary endothelial dysfunction." (PMID 33171330, 2021). "At the early stage of obesity, IL-6 probably induces ATM polarization and inflammation, whereas it antagonizes inflammation at the late onset of obesity when CLS formations are dominant." (PMID 34504646, 2021). "Inflammatory signals, like IL-1β, TNF-α, IL-6, and TLR ligands, have all been shown to impact the HSC pool during acute and chronic inflammation and, interestingly, are also all elevated during obesity." (PMID 33554957, 2021). "In contrast, IL-6 promotes muscle catabolism in concert with TNF-α under chronic inflammatory states, such as infection and obesity." (PMID 33807573, 2021). "Taken with current bioinformatic findings, the key therapeutic targets of IL-6, CCL2 in metformin treating obesity/hypertension were identified through molecular docking validation." (PMID 34334083, 2021). "Elevated interleukin-6, CRP, adipokines, cytokines, and interferons in obesity characterize a chronic low-grade inflammation." (PMID 34178545, 2021). "IL-6 and MCP-1 are important markers of chronic low-grade inflammation and are also known to play a key role in the pathogenesis of obesity and IR." (PMID 33747078, 2021). "An increase in circulating levels of cytokines (IL-1β, IL-6, and IL-17A) and their production under the influence of the HFCD diet is also specific for the development of diet-induced obesity and metabolic syndrome." (PMID 33670919, 2021). "In our study, upregulated NEU1 offset the effects of miR-23b-3p on body weight, fat percent, FBG, FI and AUC of both OGTT and ITT, and inflammatory factors (CRP, IL-6, TNF-α, MCP1) in mice with obesity-induced IR." (PMID 33781239, 2021). "In obesity, proinflammatory cytokines, such as TNF and IL-6, are produced predominantly by adipose tissue macrophages." (PMID 34201844, 2021). "In the children with obesity group, ALT and BChE levels correlated with anthropometric measurements, insulin resistance, and lipid parameters, leptin, interleukin-6, CRP, and sICAM-1 while BChE levels negatively correlated with adiponectin." (PMID 33665176, 2021). "As obesity progresses, the accumulation of inflammatory M1 ATMs becomes a major source of pro-inflammatory cytokines such as TNF-α and IL-6, which can lead to insulin resistance via activation of endocrine signaling." (PMID 33947969, 2021). "It is now well known that obesity is characterized by a state of chronic low-grade inflammation; that is, obesity induces pro-inflammatory cytokines such as tumor necrosis factor-alpha (TNF-α) and IL-6." (PMID 33557015, 2021). "During obesity, macrophages accumulate in the adipose tissue and shift to a pro-inflammatory state, exemplified by increased expression of IL-1β, TNF and IL-6." (PMID 34201844, 2021). "In obesity, circulating levels of proinflammatory cytokines, including TNF-α and IL-6, are elevated and the main sources of these inflammatory mediators are hepatic and white adipose macrophages." (PMID 32971975, 2020). "Obese mice produce high levels of proinflammatory cytokines, including TNF- α, IL-1 β, IL-6, and PAI-1, in liver and adipose tissue, and obesity is characterized by infiltration and activation of immune cells in liver and adipose tissues." (PMID 33551809, 2020). "In summary, we demonstrated the effect of IL-6 on differentiation and senescence of BMSCs in HFD-induced obesity." (PMID 33679606, 2020).
Obesity (continued). "Leptin levels, on the other hand, are elevated in obesity and are positively correlated with levels of inflammatory cytokines, namely IL1 beta, IL6 and IL12 amongst others." (PMID 32069845, 2020). "M1 pro‐inflammatory macrophages induced the secretion of IL‐1β, IL‐6, IL‐12, TNF‐α, CCL5 and CCL2 in adipose tissue during obesity." (PMID 32458441, 2020). "From literature reviews on obesity-related genes, the role of pro-inflammatory cytokines (TNF-α, IL-6, IL-1) is known, while that of anti-inflammatory molecules is less studied." (PMID 32228494, 2020). "In this study, we used IL-6 gene knockout (IL-6 KO) mice to investigate the effect of IL-6 on bone metabolism and the potential mechanism in HFD-induced obesity." (PMID 33679606, 2020). "We hypothesized that the three most common characteristics of OSAS (severity of OSAS, sex, and obesity) may have an interaction effect on the risk of cardiovascular events as determined by the serum levels of the three most representative inflammatory markers (CRP, IL-6, and TNF-α)." (PMID 32629899, 2020). "The production of inflammatory mediators, including monocyte chemoattractant protein-1 (MCP-1), interleukin (IL)-6, IL-1β, and tumor necrosis factor (TNF)α, increases with obesity since macrophages contribute to the production of them." (PMID 32019160, 2020). "The authors also showed that high-fat diet induced obesity resulted in systemic low-grade inflammation and increased proinflammatory cytokines expression in plasma (i.e., TNF-α, IFN-γ, IL-6, MCP-1β, IL-1, and IL-17)." (PMID 32887419, 2020). "In addition, high lard diet (45% fat energy) was reported to up-regulated the expression of interleukin-6 and monocyte chemoattractant protein-1 in the retroperitoneal adipose tissue of mice, which promoted the development of inflammation that contribute to obesity." (PMID 32113467, 2020). "In obesity, adipose tissue inflammation leads to increased secretion of proinflammatory cytokines (e.g., tumor necrosis factor alfa (TNF-α) and interleukin 6 (IL-6)) and adipokines (e.g., leptin, adiponectin, resistin, and irisin)." (PMID 33204675, 2020). "Our results showed, for the first time, that the IL-6 may be involved in the potential mechanism of HFD-induced trabecular bone loss by breaking the balance between osteogenesis and adipogenesis of BMSCs and promoting senescence of BMSCs in HFD-induced obesity." (PMID 33679606, 2020). "M1 macrophages release pro-inflammatory and chemokines, such as TNF-α, IL-6, and MCP-1, which can directly promote the migration of macrophages and further promote obesity-induced inflammation." (PMID 33298044, 2020). "GIP also increases IL-6 expression and production in adipocytes in the presence of TNF-α, which is induced by obesity and enhances HFD-induced insulin resistance through IL-6 signaling." (PMID 31977316, 2020). "A significant decrease of IL-6 and TNF-α levels were observed in the liver of HFD-induced obesity model after exposure to several natural products and their fermented products." (PMID 32948162, 2020). "Macrophages, which in lean people show an M2 anti-inflammatory phenotype, during obesity are switched to an M1 pro-inflammatory profile, expressing tumor-promoting cytokines, such as TNF, IL-6, IL-1β and chemokines, such as CCL2 and MIF." (PMID 32650452, 2020). "In our study, increased levels of resistin, TNF-α, IL-1β, and IL-6 were observed in the spleen in DIO mice, which suggested that the changes of cytokine in the spleen in obesity were indicative of altered immune functions." (PMID 32104715, 2020). "The DIO rats displayed obesity, increased SAP, lipids metabolism disorders, damaged morphology of liver, kidney and spleen, disturbed iron metabolism, increased IL-6 level and hepcidin mRNA expression, and decreased Epo compared to CON rats." (PMID 33292270, 2020). "Raised interleukin-6 (IL-6) and tumour necrosis factor alpha are antecedent to insulin resistance (IR), and subsequently T2DM and obesity." (PMID 30854996, 2020).
Obesity (continued). "In obesity, activated WAT and the resident macrophages secrete inflammatory cytokines, such as TNF-α, IL-6, and IL-1β into the bloodstream, which stimulates hepatocytes and Kupffer cells." (PMID 33187321, 2020). "We found a regulation of IL-6, IL-8, IL-15, IL-18, and FGF21 in plasma by exercise, while obesity status increased IL-13 and decreased IL-8 and SPARC in the circulation." (PMID 32132925, 2020). "In summary, current knowledge about the roles of IL-6 in differentiation and senescence of BMSCs is limited in HFD-induced obesity." (PMID 33679606, 2020). "The extract of fermented Moringa oleifera decreases hepatic lipid accumulation, upregulates lipid metabolic genes, as well as decreases pro-inflammatory cytokine (IL-6 and IL-12) mRNA expressions in the liver of HFD-induced obesity model." (PMID 32948162, 2020). "Relationships between higher levels of maternal inflammation markers (e.g., CRP or IL-6 and TNF-alpha inflammatory cytokines) and higher birth weight and obesity in the offspring have also been observed." (PMID 32213887, 2020). "In obesity, adipose tissue exhibited the lower activities of antioxidant enzymes (CAT, SOD, and GSH-Px) and the higher levels of cytokines (TNF-α, IL-1β, and IL-6) and ROS generation." (PMID 32104715, 2020). "Leptin concentration in plasma is increased in obesity, and high levels of leptin lead to the production of pro-inflammatory cytokines, including TNF-α and IL-6." (PMID 32796637, 2020). "In the same study, overexpression of lamin A/C in mouse macrophages revealed chronic inflammation by upregulation of mediators like IL6, TNFα and CCL2 and the development of obesity-induced insulin resistance." (PMID 32872320, 2020). "Although the etiology of obesity and IBD is different, both are characterized by gut inflammation with common inflammatory pathways including TNFα, IL6, and IL1b54–57." (PMID 32999402, 2020). "Obesity is thought to lead to increased Toll-like receptor 4 (TLR4) stimulation in adipocytes via a variety of ligands, and expression of both IL-6 and MCP1 by adipocytes can be induced by inflammation." (PMID 32603641, 2020). "Both obesity and hyperglycemia promote the release of inflammatory mediators, like TNF-α, or IL-6, released mediators stimulate macrophages and other innate immune cells, as well as some apoptosis-related signaling pathways, such as Fas/FasL signaling pathway." (PMID 32982969, 2020). "A study reported that increased body mass index (BMI) was associated with increase in two proinflammatory colonic cytokines, namely TNF-α and interleukin 6 (IL6), while obesity coincided with precancerous changes in the transcriptome." (PMID 33364203, 2020). "Oxidative stress plays a significant role in promoting interleukin 6 (IL-6) and monocyte chemotactic protein-1 (MCP-1) expression, which lead to the recruitment of monocytes and macrophage in PVAT and the pathology of obesity-induced vascular diseases." (PMID 32630640, 2020). "For that purpose, we focused on IL‐6, IL‐10, and TNF‐α, key pro‐ and anti‐inflammatory cytokines known to be dysregulated in obesity." (PMID 32614494, 2020). "An increase in the levels of pro-inflammatory cytokines and proteins such as interleukin-6 (IL-6), tumor necrosis factor alpha (TNF-α), leptin or C-reactive protein (CRP) in both blood and adipose tissue itself was observed as obesity progressed." (PMID 32555600, 2020). "We observed elevated levels of IL-6 and MCP-1 in the cornea, consistent with the recognition of obesity as a low-grade systemic proinflammatory state." (PMID 32886728, 2020). "As obesity progresses, proinflammatory adipokines, including leptin, TNF, resistin, IL-6, RBP4, lipocalin-2, and ANGPTL-2, are preferentially synthesized and cause chronic inflammation." (PMID 33133214, 2020).